HNRNPH2 (heterogeneous nuclear ribonucleoprotein H2)
Description:
This protein is a component of the heterogeneous nuclear ribonucleoprotein (hnRNP) complexes which provide the substrate for the processing events that pre-mRNAs undergo before becoming functional, translatable mRNAs in the cytoplasm. Binds poly(RG).
Synonyms: FTP3; HNRPH2; hnRNPH'; HNRPH'; MRXSB; NRPH2
Tractability: PROTAC: UniProt records ubiquitination sites on it; ubiquitination databases record sites on it; its protein half-life has been measured.
Gene: Protein-coding gene on chromosome X (101,408,114 to 101,414,137, forward strand). Ensembl gene ENSG00000126945.
Subcellular location: Nucleus, nucleoplasm
Subcellular location (Human Protein Atlas): Nucleoplasm
Pathways (Reactome):
Metabolism of RNA: Processing of Capped Intron-Containing Pre-mRNA; mRNA Polyadenylation; mRNA Splicing - Major Pathway
Disease: Dengue Virus-Host Interactions
Gene Ontology:
Molecular function: protein binding; RNA binding; nucleic acid binding
Biological process: regulation of RNA splicing
Cellular component: membrane; nucleoplasm; ribonucleoprotein complex; nucleus
Gene-disease validity (ClinGen):
ClinGen rates the evidence that HNRNPH2 causes each of these diseases.
X-linked complex neurodevelopmental disorder (X-linked): Definitive. A complex neurodevelopmental disorder that is transmitted via X-linked inheritance, and is characterized by intellectual disability, autism and epilepsy.
Homologues: Orthologues: macaque HNRNPH2 (100% identical), dog HNRNPH2 (99% identical), guinea pig HNRNPH2 (99% identical), pig HNRNPH2 (99% identical), mouse Hnrnph2 (99% identical), rat Hnrnph2 (99% identical). Paralogues in human: HNRNPH1 (96% identical), HNRNPF (69% identical), HNRNPH3 (49% identical), GRSF1 (33% identical), ESRP1 (29% identical), ESRP2 (27% identical), RBM12B (22% identical), RBM12 (20% identical).
Diseases named in the same sentence as HNRNPH2 in open-access papers:
HNRNPH2 is named in the same sentence as 30 diseases in open-access papers, as found by Europe PMC text mining. Sharing a sentence is not in itself a finding about the gene and the disease. The quoted sentences say what the papers report.
developmental delay (5 papers, 2019 to 2024). "hnRNPH2-related neurodevelopmental disorder (NDD) is caused by mutations in the HNRNPH2 gene and is associated with substantial challenges, including developmental delay, intellectual disability, growth delay, and epilepsy." (PMID 37463443, 2023). "In humans, pathogenic variants in HNRNPH2 are associated with developmental delay, most often characterized by significant motor abnormalities accompanied by severe expressive and receptive language impairment; thus, we first focused on motor function." (PMID 37463454, 2023). "Mutations in HNRNPH2 cause an X-linked neurodevelopmental disorder with features that include developmental delay, motor function deficits, and seizures." (PMID 37463454, 2023). "Of those, the majority were novel, including a loss-of-function (LOF) variant in HNRNPH2 gene, which was hemizygous in a maternal uncle and nephew (Family F133) that presented with severe ID, epilepsy, autism, developmental delay, and dysmorphic features." (PMID 31316545, 2019). "De novo pathogenic variants in HNRNPH2 were identified in 2016 in 6 unrelated individuals as a novel cause of an X-linked neurodevelopmental disorder, the features of which include developmental delay, intellectual disability, autism spectrum disorder, tone abnormalities, and seizure (OMIM 300986)." (PMID 37463454, 2023).
Intellectual disability (5 papers, 2021 to 2024). "Mental retardation, X-linked, syndromic, Bain type (MRXSB; OMIM 300986) is associated with heterozygous mutation in HNRNPH2, the gene encoding the RBP hnRNP H2." (PMID 34564083, 2021).
epilepsy (4 papers, 2019 to 2025). A brain disorder characterized by episodes of abnormally increased neuronal discharge resulting in transient episodes of sensory or motor neurological dysfunction, or psychic dysfunction. "Pathogenic variants in the heterogeneous nuclear ribonucleoprotein H2 (HNRNPH2) gene cause “Bain type” syndromic X-linked ID, with possible coexistence of epilepsy." (PMID 34440332, 2021).
melanoma (3 papers, 2019 to 2025). A malignant, usually aggressive tumor composed of atypical, neoplastic melanocytes. "RNA sequencing following the siRNA-mediated knockdown of hnRNPH2 in melanoma cells revealed an enrichment of immune-related signaling pathways." (PMID 41301529, 2025). "Results of nCounter analysis of hnRNPH1 and hnRNPH2 expression after siRNA treatment in melanoma cells and primary adult melanocytes." (PMID 41301529, 2025). "The NanoString assays revealed significantly lower gene expression levels of hnRNPH1 and hnRNPH2 in untreated melanocytes compared to untreated melanoma cell lines, consistent with our group’s previous Western blot findings." (PMID 41301529, 2025). "The results revealed that hnRNPH1 and hnRNPH2 gene expression levels were significantly lower in melanocytes compared to melanoma cell lines." (PMID 41301529, 2025). "The effect on hnRNPH2 expression was significantly greater in melanoma cell lines, suggesting that the downstream effects of knockdown are mostly due to hnRNPH2 expression changes." (PMID 41301529, 2025). "The results presented in this study demonstrate the impact of 2155-14, 2155-18, and hnRNPH2 siRNA in downregulating spliceosomal proteins hnRNPH1 and hnRNPH2 in melanoma cells." (PMID 41301529, 2025). "To further investigate the correlation between hnRNPH1 and hnRNPH2 expression and melanoma, we compared their expression levels in melanoma cell lines and melanocytes from NanoString gene expression analysis." (PMID 41301529, 2025). "Our results indicated that treating melanoma cell lines with 2155-14 and 2155-18 led to hnRNPH1/H2 downregulation, whereas hnRNPH2 siRNA treatment led to only hnRNPH2 downregulation." (PMID 41301529, 2025). "Directed global enrichment analysis in A375 melanoma cells revealed that treatment with 2155-14 and 2155-18 activated more signaling pathways compared to hnRNPH2 siRNA treatment." (PMID 41301529, 2025). "In the present study, we demonstrate the effect of pharmacological and siRNA-mediated downregulation of hnRNPH2 on stimulation of pro-inflammatory signaling in melanoma cells." (PMID 41301529, 2025). "Additionally, it is also possible that the hnRNPH2 in melanoma cells interacts with a different repertoire of client pre-mRNAs than in melanocytes." (PMID 41301529, 2025). "In the present study, we have identified potential molecular targets of novel spliceosomal probe 2155–14 in melanoma cells – DDX1, hnRNPH2 and hnRNPA2/B1." (PMID 31573152, 2019).
virus infection (2 papers, 2020 to 2022). "Furthermore, 14 proteins that were upregulated after virus infection—including TNFaIP3, HNRNPH2, RSAD2, ISG20, IDO1, and KCNN4—also exhibited significantly increased mRNA levels relative to uninfected cells (p < 0.05)." (PMID 36423196, 2022). "However, whether chicken hnRNPH2 could undergo nucleus–cytoplasm trafficking upon virus infection, or other stimulation such as IFN-β, needs further exploration." (PMID 33123126, 2020). "On the contrary, knockdown of chicken hnRNPH2 by specific siRNA transfection significantly enhanced the chIFN-β promoter activity induced by chMDA5-N, H5N6 and H9N2 virus infection." (PMID 33123126, 2020). "Further studies showed that hnRNPH2 could inhibit the chIFN-β promoter activity induced by chMDA5-N transfection, H5N6, and H9N2 virus infection in a dose-dependent manner." (PMID 33123126, 2020).
Anxiety (1 paper, 2023). Intense feelings of nervousness, tension, or panic often arise in response to interpersonal stresses. "hnRNPH2 R206W male mice have increased anxiety, impaired spatial learning and memory, deficits in social interaction, and reduced marble burying." (PMID 37463454, 2023).
breast carcinoma (1 paper, 2021). "For example, the β-deletion has been shown or speculated to be regulated by RMB10 in pancreatic cancer; NOVA1/PTBP1 in lung cancer; SRSF11, hnRNPH2, and hnRNPL in breast cancer; and MCPH1/BRIT1 in ovarian cancer." (PMID 33924498, 2021).
fragile X syndrome (1 paper, 2025). A genetic syndrome caused by mutations in the FMR1 gene which is responsible for the expression of the fragile X mental retardation 1 protein. "Notably, FMR1 and HNRNPH2 are two known splicing factors associated with fragile X syndrome and X-linked development disorders, they exhibited significant female-biased expression." (PMID 40866999, 2025).
glioma (1 paper, 2025). A benign or malignant brain and spinal cord tumor that arises from glial cells (astrocytes, oligodendrocytes, ependymal cells). "Although HNRNPH2 is primarily linked to neurodevelopmental disorders, may be functionally relevant in glioma, though its oncogenic potential remains unclear." (PMID 40561176, 2025).
Growth delay (1 paper, 2021). A deficiency or slowing down of growth pre- and postnatally. "In hnRNPH2, missense variants cluster significantly among probands with growth delay (p = 0.01), motor delay (p = 0.001), speech delay (p = 0.006), microcephaly (p = 0.01), hypotonia (0.003), seizures (p = 0.01), and cardiac abnormalities (p = 0.02) compared to controls." (PMID 33874999, 2021). "A subset of probands have growth delay (30.5%, n = 61/200), particularly probands with variation in HNRNPH1 (62.5%, n = 5/8), HNRNPH2 (47.8%, n = 11/23), HNRNPR (90%, n = 9/10, significantly more so than HNRNPK probands [p = 0.03]), and HNRNPUL2 (50%, n = 3/6)." (PMID 33874999, 2021).
Hydrocephalus (1 paper, 2023). Hydrocephalus is an active distension of the ventricular system of the brain resulting from inadequate passage of CSF from its point of production within the cerebral ventricles to its point of absorption into the systemic circulation. "hnRNPH2 P209L and R206W mice often had domed heads, typically associated with hydrocephalus that develops before ossification of the cranial sutures." (PMID 37463454, 2023). "hnRNPH2 P209L and R206W mice, but not KO mice, have craniofacial abnormalities and increased incidence of hydrocephalus." (PMID 37463454, 2023). "Neither male nor female Hnrnph2-KO mice showed increased incidence of hydrocephalus compared with WT littermates." (PMID 37463454, 2023). "Although the C57BL/6J background has a relatively high incidence of hydrocephalus (0.029% at The Jackson Laboratory), the number of mice with pathologically confirmed hydrocephalus suggested an increased incidence in hnRNPH2 P209L and R206W mutant mice, but not in KO mice, compared with WT controls." (PMID 37463454, 2023).
prostate carcinoma (1 paper, 2023). A carcinoma that arises from epithelial cells of the prostate gland. "With siRNA screens, several of these were indicated in survival (DDX6, EIF4A3, PABPN1), growth (e.g., EIF5A, HNRNPH2, LRRC47, and NVL), and migration (e.g., NOL3 and SLTM) of prostate cancer cells." (PMID 37591798, 2023).
Schaaf-Yang syndrome (1 paper, 2022). "These include disorders such as Schaaf-Yang syndrome (MAGEL2), which had only one variant in our cohort, or HNRNPH2-related NDD, which had no variants in our cohort." (PMID 36359385, 2022).
cancer (7 papers, 2018 to 2023). A tumor composed of atypical neoplastic, often pleomorphic cells that invade other tissues. "We previously analyzed the expression levels of HNRNPF and HNRNPH1 or HNRNPH2 on normal and several types of cancer tissues." (PMID 34563043, 2021). "Accordingly, HNRNPH2 expression is increased in cancer (mean transcripts per million [TPM] 57.88 vs. 46.29, P value < 2.2e−16; Mann–Whitney–Wilcoxon test)." (PMID 30120239, 2018). "HNRNPs participated in cancer‐related pathways including protein secretion, mitotic spindle, G2/M checkpoint, DNA repair, IL6/JAK/STAT3 signal and coagulation, of which hnRNP genes of HNRNPF, HNRNPH2, HNRNPU and HNRNPUL1 are more likely to be implicated." (PMID 32915499, 2020). "Differentiating into the 27 TCGA cohorts, we observe a significant correlation in 11 individual cancer types (FDR for Spearman correlation < 5%), all negative, suggesting that HNRNPH2-mediated repression of RON exon 11 commonly occurs in human cancers." (PMID 30120239, 2018). "While hnRNPH2 and hnRNPH1 have not been considered for cancer drug discovery, there are molecules that bind other spliceosomal components that are being investigated for cancer therapy." (PMID 31573152, 2019).
neurodevelopmental disorder (7 papers, 2022 to 2025). A behavioral and cognitive disorder with onset during the developmental period that involves impaired or aberrant development of intellectual, motor, or social functions. "Our group first identified the X-linked RNA-binding protein, HNRNPH2 (heterogeneous nuclear ribonucleoprotein H2) to be causative of a neurodevelopmental disorder, with some individuals reporting a formal RTT diagnosis from a clinician provider." (PMID 37372334, 2023). "More than 90% of individuals with HNRNPH2-related neurodevelopmental disorder have a nonsynonymous single nucleotide variant within or adjacent to the nuclear localization signal (NLS) of hnRNPH2, with the 2 most common missense variants, R206W and R206Q, located within the NLS." (PMID 37463454, 2023). "Among them, HNRNPH2 and LSM1 have been implicated to be associated with various neurodevelopmental disorders in numerous studies." (PMID 40288647, 2025). "In addition, pathogenic variants in HNRNPU (OMIM #602869), HNRNPK (OMIM #600712), HNRNPH2 (OMIM #300610), HNRNPH1 (OMIM #601035), and HNRNPR (OMIM #607201) were identified in individuals affected by various neurodevelopmental disorders." (PMID 34907471, 2022).
infection (2 papers, 2021 to 2024). The state of being infected such as from the introduction of a foreign agent such as serum, vaccine, antigenic substance or organism. "Most candidate proteins such as PLA2G4A, FASN, HNRNPH2, and LARP4 showed detectable cleavage products at 5 h.p.i. that were stable at later times of infection." (PMID 38953667, 2024).
tumor (2 papers, 2021 to 2024). "Proteins that were perturbed in expression level in the peripheral or in the central part of the tumor as compared with the non-involved part included S100A11, HNRNPF, HNRNPH1 or HNRNPH2, GSTP1, PKM and FABP1." (PMID 34563043, 2021).
neuromuscular disease (1 paper, 2025). "Through correlation analysis between selected SFs with neuromuscular disease associated devASGs, along with data from HNRNPH2 knockout experiments, we validated the potential regulatory role of these SFs in human specific splicing variations." (PMID 40288647, 2025). "Moreover, the splicing changes induced by HNRNPH2 knockout in human neurons were predominantly enriched in genes associated with neuromuscular diseases." (PMID 40288647, 2025).
HNRNPH2 also shares sentences with these, for which no sentence is quoted: autism (1 paper); autism spectrum disorder (1); Ewing sarcoma (1); Fabry disease (1); glioblastoma (1); lung carcinoma (1); microcephaly (1); myositis (1); neuroblastoma (1); obsessive-compulsive disorder (1); ovarian carcinoma (1); pancreatic cancer (1).